ZFHX3 (zinc finger homeobox 3)
Diseases named in the same sentence as ZFHX3 in open-access papers (continued):
Sharing a sentence is not in itself a finding about the gene and the disease.
prostate carcinoma (continued). "Interestingly, genomic gains in the transcription factor ZFHX3 could also be found in circulating tumor cells from prostate cancer patients." (PMID 28915599, 2017). "Previously, the same combined inactivation of ZFHX3 and PTEN was found to drive the progression of prostate cancer in a mouse model." (PMID 36613756, 2022). "Like ERβ, ZFHX3 also suppressed cell proliferation and MYC expression in prostate cancer cells, and downregulation of MYC was necessary for the suppressive effect of ZFHX3 on cell proliferation." (PMID 30979864, 2019). "Whereas the suppressive role of ZFHX3 in prostate cancer has been established in mouse knockout models, the role of ZFHX3 has not been systematically examined in human prostate cancer cell lines." (PMID 30979864, 2019). "Therefore, it appears that at least in some AR‐positive prostate cancer cells, AR is present in the nucleus even in the absence of androgen, and such androgen‐independent AR binds to the ZFHX3 promoter to repress its transcription." (PMID 34953044, 2022). "Our findings indicate that being part of ERβ signaling is an important mechanism for ZFHX3’s tumor suppressor activity in prostate cancer, as ZFHX3 is clearly upregulated by activated ERβ in C4-2B cells, and repression of MYC transcription by ERβ required the interaction of ERβ with ZFHX3." (PMID 30979864, 2019). "Although one region of the MYC promoter was bound by both ZFHX3 and ERβ, another region was only bound by ZFHX3 and not by ERβ, further indicating that ZFHX3 is a bona fide repressor of MYC transcription in prostate cancer cells." (PMID 30979864, 2019).
Stroke (22 papers, 2010 to 2026). Sudden impairment of blood flow to a part of the brain due to occlusion or rupture of an artery to the brain. "Given its involvement in cardiac conduction and AF, ZFHX3 is considered a genetic marker for stroke risk, particularly concerning arrhythmia-induced events." (PMID 39997650, 2025). "Variants in the ZFHX3 gene have been linked to increased susceptibility to AF, thus elevating the risk of stroke due to embolic events." (PMID 39997650, 2025). "However, in ischemic stroke, two genes (PITX2 and ZFHX3), located in the short arms of chromosomes 4 (4q25) and 16 (16q22), respectively, have been reported as significant risk factors for stroke." (PMID 35741740, 2022). "Very recently a SNP in ZFHX3 gene has been associated with AF and with CE stroke." (PMID 21804778, 2010). "For instance, polymorphisms in the PITX2 and ZFHX3 genes were associated with cardioembolic stroke, while markers in the 9p21 locus and the HDAC9 gene were associated with atherothrombotic stroke." (PMID 37893101, 2023). "More specifically, the genes PITX2/C4orf32 and ZFHX3 possessed a relation to stroke, while the genes KLHL3/WNT8A, HCN4/ C15orf60, and SLC35F1/PLN were found to be phenotypically associated with heart rate." (PMID 37270590, 2023). "A single-nucleotide polymorphism in the PITX2 and ZFHX3 genes and two other significantly associated genes, ZNF566 and PDZK1IP1, increase the risk of stroke." (PMID 35741740, 2022). "To date, a stroke can be genetically associated with multiple susceptibility loci, including 9p21 (CDKN2A/CDKN2B/ANRIL), 7p21 (HDAC9), 6p21.1, 4p25 (PITX2), 16q22 (ZFHX3), 9q34 (ABO)." (PMID 33808851, 2021). "AF and stroke are related and ZNF566, PDZK1IP1, ZFHX3, and PITX2 genes are significantly associated with novel biomarkers involved in AF-related stroke." (PMID 30760287, 2019). "Furthermore, genetic loci (specific regions of human DNA) such as 9p21, PITX2, ZFHX3, FOXF2, and GUCY1A3 have been implicated in stroke susceptibility and subtype differentiation." (PMID 41018177, 2025). "Among these, ZFHX3 and SH2B3 have already been established as linked to stroke." (PMID 39997650, 2025). "Thus, there is an association between AF and stroke, and expression of ZNF566, PDZK1IP1, ZFHX3, and PITX2 genes favor AF-related stroke." (PMID 30760287, 2019). "Furthermore, genome-wide association studies (GWAS) have identified loci such as 9p21, PITX2, ZFHX3, FOXF2, and GUCY1A3 as significant contributors to stroke risk and subtype differentiation, underscoring the interplay of genetic, metabolic, and demographic factors in stroke etiology." (PMID 41018177, 2025). "Finally, co-expressed DEGs of ZNF566, PDZK1IP1, ZFHX3, and PITX2 coupled with corresponding predicted miRNAs, especially miR-27a-3p, miR-27b-3p, and miR-494-3p may be significantly associated with AF-related stroke." (PMID 30760287, 2019). "Specifically, 3 genes have been associated with atherothrombotic stroke subtype (HDAC9, CDKN (locus 9p21) and TSPAN2), 2 genes with cardioembolic stroke subtype (PITX2 and ZFHX3), and 2 genes with young strokes (ABO and MMP12)." (PMID 29321829, 2018). "To date, only a handful of robust SNP associations have been identified for cardioembolic stroke (PITX2, ZFHX3), large-artery atherosclerotic stroke (9p21, HDAC9), and more recently, for all subtypes of stroke (12q24)." (PMID 25906364, 2015). "In the same year, and with a sample size of 16,851 cases and 32,473 non-stroke controls, the NINDS Stroke Genetics Network (SiGN) found a new locus associated with LAS close to TSPAN2 and confirmed the previous loci ABO, HDAC9, PITX2, and ZFHX3." (PMID 35743317, 2022). "Additionally, co-DEGs of ZNF566, PDZK1IP1, ZFHX3, and PITX2 link AF and stroke." (PMID 30760287, 2019).
Stroke (continued). "In this review we update current knowledge about biomarkers related with cardioembolic stroke etiology (such as BNP and D-dimer proteins, or PITX2 and ZFHX3 genes), that in the future, might allow rapidly guiding other diagnostic tests and accelerating the onset of an optimal secondary prevention." (PMID 21804778, 2010).
breast carcinoma (21 papers, 2008 to 2025). "Acting as a tumor suppressor, ZFHX3 has been implicated in prostate and breast cancers, and is frequently mutated in microsatellite unstable endometrial (36%) and colorectal (approximately 40%) tumors." (PMID 41413856, 2025). "ZFHX3 loss promotes ESR1-mediated cell proliferation in ESR1-positive breast cancer cells by upregulating breast cancer stem cells and MYC transcription, and similar findings have been reported in androgen receptor-positive prostate cancer." (PMID 41413856, 2025). "The transcription factor ZFHX3 is rarely mutated, but its mRNA expression level is almost systematically reduced in breast cancer cell lines." (PMID 36613756, 2022). "The first differentially methylated site (cg10298059) is annotated to the gene body of ZFHX3, which is a transcription factor and tumor suppressor gene, its expression associated with the prognosis of breast cancer patients." (PMID 35751095, 2022). "Here, we found that ZFHX3 promoted the proliferation and tumor growth of breast cancer cells in culture and nude mice; and higher expression of ZFHX3 in human breast cancer specimens was associated with poorer prognosis." (PMID 33217982, 2020). "ZFHX3 has been implicated in mammary gland stemness, and BCSCs are proposed to drive breast cancer initiation and progression." (PMID 33217982, 2020). "In this study, we examined the role of ZFHX3 in the regulation of breast cancer growth and potential underlying mechanisms." (PMID 33217982, 2020). "In the BreastMark database, higher levels of ZFHX3 mRNA is also associated with poor survival in breast cancer patients." (PMID 33217982, 2020). "The ZFHX3 gene is sometimes mutated but more often downregulated in mammary carcinomas." (PMID 36613756, 2022). "Previous study reported that ZFHX3 is involved with proliferation of breast cancer cells by enhancing MYC and TBX3 transcription, which was well recapitulated in our data." (PMID 40312397, 2025). "Whole exome sequencing of invasive mammary carcinomas revealed the association of mutations in PTEN and ZFHX3 tumor suppressor genes (TSGs)." (PMID 36613756, 2022). "SUMOylation of ZFHX3 increases its stability via preventing its ubiquitination, which is essential for ZFHX3 to promote cell proliferation in breast cancer cell lines." (PMID 35859792, 2022). "A promoting effect of ZFHX3 on breast cancer is further supported by the correlation of higher ZFHX3 expression levels with worse patient survival in breast cancer patients of the TCGA database." (PMID 33217982, 2020). "We further evaluated the role of ZFHX3 in breast cancer by comparing breast cancers with lower and higher ZFHX3 mRNA expression levels for patient survival using data from the Cancer Genome Atlas (TCGA) database." (PMID 33217982, 2020). "To further test how ZFHX3 impacts breast cancer growth, we injected T-47D cells with ectopic expression of ZFHX3 into the mammary fat pads of nude mice and analyzed their tumorigenicity." (PMID 33217982, 2020). "In summary, these findings suggest that transcription factor ZFHX3 plays a promoting function in breast cancer cells’ proliferation and tumor growth involving the BCSC properties." (PMID 33217982, 2020). "We also explored how ZFHX3 modulates breast cancer growth by focusing on breast cancer stem cell (BCSC) features and ZFHX3′s downstream target genes." (PMID 33217982, 2020). "ZFHX3 also enhanced breast cancer stemness, as indicated by ZFHX3-induced increases in mammosphere formation and the populations of ALDH+ or CD44+/CD24− cells, and cancer stemness is crucial for tumor initiation and progression." (PMID 33217982, 2020). "In our previous study, where ZFHX3 inhibited the proliferation of breast cancer cells, cells were cultured in the hormone-free medium for three days to eliminate the effect of other hormones." (PMID 33217982, 2020).
breast carcinoma (continued). "In this study, the authors aim to determine if ZFHX3 promotes breast cancer cells’ proliferation and tumor growth and explore the underlying cellular and molecular mechanisms." (PMID 33217982, 2020). "ZFHX3 regulates mammary epithelial cells’ proliferation and differentiation by interacting with estrogen and progesterone receptors, potent breast cancer regulators." (PMID 33217982, 2020). "Results from the in vivo model further indicate that ZFHX3 increases xenograft tumor growth of breast cancer cells." (PMID 33217982, 2020). "Taking these findings together, we conclude that ZFHX3 promotes breast cancer growth, at least in a subset of patients." (PMID 33217982, 2020). "Enhancing stemness via transcriptional activation of multiple stem cell factors is a possible mechanism for ZFHX3 to promote breast cancer cells’ proliferation and tumor growth." (PMID 33217982, 2020). "In this study, we examined the role of ZFHX3 in breast cancer cells’ proliferation and tumor growth using in vitro and in vivo models." (PMID 33217982, 2020). "Combining ER and PR’s roles in breast cancer and their interactions with ZFHX3, it is likely that ZFHX3 plays a role in breast carcinogenesis." (PMID 33217982, 2020). "Our findings in this study indicate that ZFHX3 plays a promoting role in breast cancer, as its knockdown attenuated, while its ectopic expression promoted, the proliferation and tumorigenicity of breast cancer cells in both in vitro and in vivo models." (PMID 33217982, 2020). "For example, ERα not only regulates the expression of ZFHX3 but also interacts with ZFHX3 to regulate gene expression and cell proliferation in breast cancer cells." (PMID 30979864, 2019). "We found genetic alterations of PTEN and ZFHX3 in tumors of breast cancer patients." (PMID 36613756, 2022). "Moreover, low levels of ZFHX3 are strongly correlated with poor prognosis of breast cancer patients." (PMID 36613756, 2022). "Both these receptors play crucial roles in breast cancer development, but whether ZFHX3 also impacts breast cancer is unknown." (PMID 33217982, 2020). "We should mention that OCT4, NANOG, and SOX2 could also explain the effect of ZFHX3 on BCSC features as they are known stem cell factors, and their expression was also upregulated by ZFHX3 in breast cancer cells." (PMID 33217982, 2020). "We report that ZFHX3 enhances cell proliferation and tumor growth of ER+ breast cancer cells." (PMID 33217982, 2020). "Higher ZFHX3 expression is associated with worse patient survival in breast cancer, ZFHX3 promotes the proliferation and tumor growth of breast cancer cells, and several breast cancer stem cell factors appear to be involved in the role of ZFHX3 in breast cancer growth." (PMID 33217982, 2020). "To test whether ZFHX3 modulates breast cancer cell proliferation and tumorigenicity, we first surveyed the levels of endogenous ZFHX3 expression in 5 breast cell lines by western blotting." (PMID 33217982, 2020). "ZFHX3 thus plays a promoting role in breast cancer cell proliferation in vitro." (PMID 33217982, 2020). "The findings suggest that ZFHX3 is a novel oncogenic molecule promoting breast cancer development." (PMID 33217982, 2020). "Therefore, the role of ZFHX3 in breast cancer appears to be context-dependent." (PMID 33217982, 2020). "Therefore, although enhanced breast cancer stemness could be a cellular mechanism that is partially responsible for the tumor-promoting effect of ZFHX3 in breast cancer, a firm role of ZFHX3 in the maintenance of BCSCs remains to be established." (PMID 33217982, 2020). "TRIM25 has also been shown to be regulated by estrogen receptor alpha in breast cancer and to mediate ubiquitination and degradation of two transcription factors: KLF5 and ZFHX3." (PMID 27626314, 2016).
breast carcinoma (continued). "For example, SUMOylation at Lys-2806 of zinc finger homeobox 3 (ZFHX3) enhances the stability of ZFHX3 by interfering with its ubiquitination and proteasomal degradation, while the ZFHX3 K2806R mutant decreases its protein stability, further suppressing breast cancer growth." (PMID 39127633, 2024).
gastric cancer (14 papers, 2008 to 2025). A primary or metastatic malignant neoplasm involving the stomach. "ZFHX3 is a candidate tumor suppressor gene for prostate, breast and gastric cancer, which acts by inducing cell cycle arrest." (PMID 35419428, 2022). "ZFHX3 may function as transcriptional regulator and was reported to participate in gastric cancer by regulating MUC5AC promoter." (PMID 30286182, 2018).
cardioembolic stroke (13 papers, 2012 to 2025). "Variants in ZFHX3 influence cardiac electrical activity, predisposing individuals to AF and subsequent cardioembolic stroke." (PMID 40676916, 2025). "This study showed that variants close to PITX2 (paired like homeodomain 2) and ZFHX3 (zinc finger homeobox 3) were linked to cardioembolic stroke." (PMID 35326259, 2022). "Large genome-wide association studies (GWAS) have found that the genetic markers close to the PITX2 gene on chromosome 4q25 and to the ZFHX3 gene on 16q22 are associated with both AF and cardio-embolic stroke." (PMID 26631084, 2015). "In addition, several studies have found that SNP rs7193343, located on ZFHX3, is associated with prognostic recovery in cardioembolic stroke, a subtype of IS." (PMID 37323662, 2023). "ZFHX3 (16q22) and PITX2 (4q25) variants are two of the most potent GWAS indicators for AF and cardioembolic stroke." (PMID 40863347, 2025). "The discovery meta-analysis confirmed associations at genome-wide significance levels for HDAC9 with large-vessel disease, and for both PITX2 and ZFHX3 with cardioembolic stroke." (PMID 23041239, 2012). "We verified previous associations for cardioembolic stroke near PITX2 (p=2·8×10−16) and ZFHX3 (p=2·28×10−8), and for large-vessel stroke at a 9p21 locus (p=3·32×10−5) and HDAC9 (p=2·03×10−12)." (PMID 23041239, 2012). "The population attributable risks in the METASTROKE discovery cohort were estimated as 5·8% for PITX2 and 7·0% for ZFHX3 in cardioembolic stroke, and 4·5% for HDAC9 and 7·2% for 9p21 in large-vessel disease." (PMID 23041239, 2012). "Thus far, only four genes (PITX2, ZFHX3, ZNF566, and PDZK1IP1) were reported to be associated with both AF and cardioembolic stroke." (PMID 38132662, 2023).
ischemic stroke (12 papers, 2012 to 2025). A stroke disorder caused by obstruction of blood flow to the brain, due to thrombotic (local blood clot formation) or embolic (due to a blood clot or other material traveling from another site) event. "A meta-analysis of GWAS on ischemic stroke identified the ZFHX3 gene on chromosome 16q22 as a locus specifically associated with atrial fibrillation and cardioembolic stroke." (PMID 26355258, 2015). "Notably, the association of ischemic stroke with ZFHX3, PITX2, the 9p21 locus, and HDAC9 was verified in the collaborative METASTROKE study in which these loci were found to be specific to particular stroke subtypes." (PMID 26355258, 2015). "Several genes, including PITX2,ZFHX3, HDAC9, FOXF2,GUCY1A3, and GCH1, havebeen identified to increase the risk of developing ischaemic stroke." (PMID 40351662, 2025). "We identified four novel eGFR-associated loci which have been previously associated with ischemic stroke in other studies, specifically USP38, ZFHX3, PMF1-BGLAP, and TTBK151–53." (PMID 31451708, 2019). "The previously reported GWAS associations from a recent ischaemic stroke meta-analysis (9p21, HDAC9, PITX2, ZFHX3) were all found to be more significant using the age-at-onset informed approach than the uninformed analysis." (PMID 25078452, 2014). "In addition, certain molecular genetic variations have been shown to be closely related to ischemic stroke, such as Paired-like homeodomain transcription factor 2 (PITX2), Histone deacetylase 9 (HDAC9), and Zinc finger homeobox protein 3 (ZFHX3)." (PMID 32228489, 2020).
Ataxia (6 papers, 2024 to 2025). Ataxia refers to impaired coordination of voluntary muscle movement. "This analysis highlights the overlap of clinical features associated with ZFHX3 expansions with more common ataxias, such as RFC1-related disorders and Friedreich’s ataxia making diagnosis challenging when relying solely on the clinical phenotype and testing for a single expansion." (PMID 40166539, 2025). "The fact that we identified five families with ZFHX3 repeat expansions from our center suggests a relatively high prevalence of this disorder, at least among persons with ataxia from southern Sweden." (PMID 38035881, 2024). "Recently, an exonic GGC repeat expansion (RE) was identified by long-read genome sequencing in the ZFHX3 gen, causing spinocerebellar ataxia type 4 (SCA4), a dominant form of ataxia with sensory neuropathy." (PMID 39095619, 2024). "The pleiotropic roles of ZFHX3 further extend in non-brain tissues with its recently described crucial involvement in angiogenesis for tumour development, cardiac function, and spinocerebellar ataxia." (PMID 40117332, 2025).
neuroblastoma (6 papers, 2008 to 2024). Neuroblastoma (NB) is the most common solid, extracranial childhood tumor. "However, to our knowledge, recurrent focal amplifications of MYC, ZFHX3, KRAS, RRAS2, and CYTH1 have not been reported in neuroblastoma primary tumors before." (PMID 28924153, 2017).
colon cancer (5 papers, 2018 to 2024). "The biology and expression levels of Zfhx3 and Pitx2c in HL-1 cells, which are of murine cardiac origin, and HCT116 cells, which are of human colon cancer origin, are likely very different." (PMID 34884836, 2021).
colorectal cancer (5 papers, 2020 to 2025). A primary or metastatic malignant neoplasm that affects the colon or rectum. "ZFHX3 mutations were also associated with a significant survival benefit across all patients, and were most common in colorectal cancer patients, followed by bladder cancer, melanoma, and NSCLC patients." (PMID 35798829, 2022). "This evidence suggests that ZFHX3 mutations may decrease colorectal cancer patients’ risk of DS-death, particularly in the context of hypermutation, through enhanced immune-related mechanisms." (PMID 41413856, 2025). "Within the sample subgroups, colorectal cancer was significantly enriched for APC mutations (40/54 colorectal cancer samples), ZFHX3 (13/54 samples) and FBXW7 (13/54)." (PMID 32306292, 2020).